AXIN2 (axin 2)
Diseases named in the same sentence as AXIN2 in open-access papers (continued):
Sharing a sentence is not in itself a finding about the gene and the disease.
lung carcinoma (25 papers, 2012 to 2025). "AXIN2 polymorphism rs2240308 was also associated with decreased cancer risk under all five models in lung cancer." (PMID 25974148, 2015). "Despite these limitations, our meta-analysis suggested that the AXIN2 rs2240308 polymorphism increases the risk of cancer, especially in lung cancer and Asian populations." (PMID 26161041, 2015). "First, as a tumor suppressor gene, AXIN2 polymorphisms on the susceptibility of cancer have been found in lung cancer, prostate cancer, and other cancers, while these cancers have all been linked to Wnt signaling." (PMID 26161041, 2015). "This study showed that the AXIN2 rs2240308 polymorphism contribute to increasing the risk of cancer, especially lung cancer in Asian populations." (PMID 26161041, 2015). "Low expression of AXIN2 was found to be associated with β-catenin accumulation in lung cancer, and epigenetic silencing of AXIN2 leads to β-catenin nuclear accumulation in tumorigenesis." (PMID 26161041, 2015). "Therefore, cumulative evidence for the association between AXIN2 polymorphisms and lung cancer was categorized as weak since there was a C." (PMID 26161041, 2015). "Our results, based on 8 articles that included 10 case-control studies with 1,502 cases and 1,590 controls, suggested that the AXIN2 rs2240308 polymorphism increases the risk of cancer in a co-dominant model (GG vs. AA) and the recessive model, especially in lung cancer and Asian populations." (PMID 26161041, 2015). "In addition, some Axin2 mutant genotypes are closely related to the low-risk lung cancer types." (PMID 35087829, 2021). "In addition to the current association between the Axin2 rs2240308 SNP and prostate cancer in the Chinese population, other studies have demonstrated a significant association between the rs2240308 SNP and lung cancer development in Japanese and Turkish populations." (PMID 25013500, 2014). "NCB-0846, but not NCB-0970, inhibited the expression of TNIK as well as the expression of Wnt target gene products, including Axin1, Axin2 and cMyc, in A549 lung cancer cells." (PMID 33244122, 2021). "Alterations of AXIN2 have been demonstrated to contribute to carcinogenesis, specifically in lung cancer, and the downregulation of this suppressor via a large methylation change was successfully detected by our method." (PMID 28178311, 2017). "The AXIN2 SNP, Pro50Ser (rs2240308, c.148G > A), results in an amino acid change from a proline to a serine, which is located at exon 1 148 of the AXIN2 gene, has been widely observed in lung cancer, ovarian cancer and prostate cancer." (PMID 26161041, 2015). "Decreased expression of AXIN has been detected in lung cancer tissues, while the expression of AXIN2 increases in CRC." (PMID 26161041, 2015). "Moreover, results from in silico tools showed that AXIN2 expressions in lung cancer and prostate cancer are lower than that in normal counterpart." (PMID 31080360, 2019). "High expression of AXIN2 may have longer OS time than low expression group for lung cancer participants, which were consistent with results derived from the present meta-analysis." (PMID 31080360, 2019). "The results indicated that the AXIN2 rs2240308 polymorphism was significantly associated with an increased risk of lung cancer but not in other cancer types." (PMID 26161041, 2015). "Among these Axin2 SNPs, a significant association between rs2240308 [guanine (G)/adenine (A); also described as 148 cytosine (C)/thymine (T), or CCT/TCT (Proline (Pro)/Serine (Ser)), or Pro50Ser] and the risk of lung cancer has been reported previously." (PMID 25013500, 2014). "Indeed, there was a significant correlation between levels of AXIN2 and the EMT markers VIM (Vimentin) and ZEB1 (Zinc Finger E-Box Binding Homeobox 1), which again was lost in tumor samples from Metformin-taking lung cancer patients." (PMID 29977599, 2018).
lung carcinoma (continued). "No significant changes in mean values of SOX4 and AXIN2 between non-diabetic and diabetic Metformin-taking lung cancer patients were detected." (PMID 29977599, 2018). "However, there was a significant correlation between SOX4 and AXIN2 mRNA levels in tumor tissues in the group of non-diabetic lung cancer patients (Spearman’s rank correlation coefficient ρ = 0.47, P < 0.0001)." (PMID 29977599, 2018).
Oligodontia (24 papers, 2014 to 2025). The absence of six or more teeth from the normal series by a failure to develop. "Oligodontia can be caused by mutations in various genes involved in tooth development, like AXIN2, MSX1, and PAX9." (PMID 40136761, 2025). "Of all these, MSX1, PAX9, EDA, and AXIN2 genes are most frequently associated with nonsyndromic hypodontia or oligodontia." (PMID 40995403, 2025). "Mutations in AXIN2 cause oligodontia–colorectal cancer syndrome (OMIM#608615), in which affected individuals have severe oligodontia and a predisposition to colon polyps and/or colon cancer." (PMID 34834569, 2021). "I add to the paucity of literature by reporting the case of a patient, with oligodontia and numerous colonic polyps, who was found to have an Axin2 mutation." (PMID 34858573, 2021). "Genetic sequencing revealed a mutation in Axin2, a rare gene implicated in oligodontia-colorectal cancer syndrome." (PMID 34858573, 2021). "Genetic testing returned positive for an AXIN2 mutation, which has been associated with oligodontia-colorectal syndrome." (PMID 34858573, 2021). "A Finnish family was described in which a nonsense mutation in AXIN2 was found to co-segregate with an oligodontia phenotype." (PMID 29274157, 2018). "In conclusion, this study report describes a de novo AXIN2 missense mutation (c.314T>G) in a Chinese individual with non-syndromic oligodontia." (PMID 26406231, 2015). "This is the first report indicating that a mutation in the RGS domain of AXIN2 is responsible for non-syndromic oligodontia." (PMID 26406231, 2015). "In the present study, we identified a de novo AXIN2 missense mutation (c.314T>G) in a Chinese individual with non-syndromic oligodontia." (PMID 26406231, 2015). "It appears that AXIN2 mutations that lead to a truncated AXIN2 protein are more likely to lead to syndromic oligodontia and predispose to cancer." (PMID 26406231, 2015). "Our study supports the relationship between AXIN2 mutation and non-syndromic oligodontia and extends the mutation spectrum of the AXIN2 gene." (PMID 26406231, 2015). "A Finnish family was described in 2004 in which a nonsense mutation in axis inhibition protein 2 (AXIN2) was found to co-segregate with an oligodontia (severe tooth agenesis) phenotype." (PMID 24607150, 2014). "However, a recent French series involving 11 unrelated individuals with AXIN2 variants revealed that oligodontia was present in only 60% of cases." (PMID 39057027, 2024). "The main two CRC syndromes associated with tooth agenesis are FAP and AXIN2 oligodontia." (PMID 35158896, 2022). "Twenty-four oligodontia cases with AXIN2 gene mutations were evaluated." (PMID 34593752, 2021). "Given the presence of an Axin2 mutation, her dental history and colonoscopy findings and her presentation not matching any known colorectal cancer syndrome, it was felt that she had or was at risk for oligodontia-colorectal cancer syndrome." (PMID 34858573, 2021). "Several researchers hypothesized that when the AXIN2 protein is mildly affected, as in cases of missense variants, individuals are more prone to non-syndromic oligodontia, whereas truncating pathogenic variants in AXIN2 are more likely to predispose carriers to both oligodontia and CRC." (PMID 35158896, 2022). "In this study, genes associated with oligodontia (MSX1, PAX9, AXIN2, and WNT10A) were analyzed in both the patient and her relatives with oligodontia, revealing the same mutation in the initial codon of the PAX9 gene." (PMID 40692763, 2025). "Mutations in numerous genes including msh homeobox 1 (MSX1), paired box 9 (PAX9), Wnt family member 10A (WNT10A), axis inhibition protein 2 (AXIN2), ectodysplasin A (EDA), and Wnt family member 10B (WNT10B) have been associated with nonsyndromic oligodontia." (PMID 30134957, 2018). "AXIN2 mutations have been regarded as causative for the segregation of CRC and oligodontia in a Finnish family." (PMID 24607150, 2014).
Oligodontia (continued). "AXIN2-associated polyposis is an autosomal dominant syndrome characterized by colorectal polyps and oligodontia, defined as a congenital absence of at least seven teeth." (PMID 39057027, 2024). "We report another putative pathogenic variant AXIN2 p.R594W found in a patient with CRC at 45 years, however, we did not have information on existence of oligodontia in this carrier, a feature previously associated with AXIN2 germline mutations." (PMID 29212164, 2017). "Our findings indicate that the novel heterozygous transition found in AXIN2 (c.314T>G) might be responsible for the presentation of non-syndromic oligodontia in the proband." (PMID 26406231, 2015). "This missense mutation (c.314T>G) may affect the function of the RGS domain of the AXIN2 protein, leading to oligodontia." (PMID 26406231, 2015). "However, AXIN2 variants previously found in patients with apparently non-syndromic oligodontia may add to the risk of polyposis/CRC later in life." (PMID 35158896, 2022). "We found a missense variant in AXIN2, but detected no pathogenic variants in MSX1, PAX9, EDA, EDAR, or EDARADD, genes that previously have been found in nonsyndromic oligodontia." (PMID 32234057, 2020). "In the present study, we investigated six genes (MSX1, PAX9, AXIN2, WNT10A, EDA and EDARADD) in a patient with sporadic non-syndromic oligodontia." (PMID 26406231, 2015).
melanoma (22 papers, 2012 to 2024). A malignant, usually aggressive tumor composed of atypical, neoplastic melanocytes. "AXIN2 mutations have been studied in different cancer entities including digestive tract tumors and melanoma." (PMID 35625787, 2022). "Nonetheless, β-catenin, APC and AXIN2 mutations are rare in primary melanoma specimens, in comparison to well-characterized melanoma cell lines cultured in vitro for a long period." (PMID 33212834, 2020). "Cinobufagin decreases LEF1 expression in a dose-dependent manner and Wnt/β-catenin target genes such as Axin-2, cyclin D1, and c-Myc in melanoma cell lines." (PMID 32933177, 2020). "Treatment of four different melanoma cell lines with Wnt3a-CM induced AXIN2 expression in comparison with 3T3-CM treated melanoma cells." (PMID 29454361, 2018). "We further demonstrate that in vivo, LY2090314 elevates Axin2 gene expression after a single dose and produces tumor growth delay in A375 melanoma xenografts with repeat dosing." (PMID 25915038, 2015). "After WNT3A stimulation, we found that AXIN2 transcripts increased in abundance in cells transfected with PKN siRNAs in all melanoma cell lines tested." (PMID 24114839, 2013). "To study whether LEF1 is required to suppress the expression of Wnt/β-catenin target genes, we analyzed c-Myc, Cyclin D1, and Axin-2 mRNA levels in LEF1 knocked-down A375 melanoma cells." (PMID 32933177, 2020). "In a panel of melanoma cell lines, nM concentrations of LY2090314 stimulated TCF/LEF TOPFlash reporter activity, stabilized β-catenin and elevated the expression of Axin2, a Wnt responsive gene and marker of pathway activation." (PMID 25915038, 2015). "We also analysed expression profiles across a spectrum of melanocytes and additional melanoma cell lines and find that the expression of WLS and AXIN2 are highly correlated (Spearman R = 0.8035, p = 0.0366)." (PMID 23129487, 2012). "It has been found that quercetin induced apoptosis in melanoma cells and destabilized the WNT-FZD-LRP6 complex by suppressing DVL2 and AXIN2, which resulted in decreased β-catenin and the inhibition of the WNT-responsive gene encoding cyclin D1 (CCND1) and cyclooxygenase (COX2)." (PMID 39684513, 2024). "Quantitative analysis of β-catenin protein as well as its functional activation, measured by quantification of mRNA levels of the ubiquitously target gene AXIN2 and of the melanocyte specific marker MITF showed a heterogeneous level of WNT pathway activation in melanoma cells." (PMID 27175588, 2016).
gastric cancer (17 papers, 2010 to 2025). A primary or metastatic malignant neoplasm involving the stomach. "In this study we explored the clinical relevance of breast and gastric cancer-associated polymorphisms in AXIN2 and CDH1 with NSCL ± P risk in the Brazilian population." (PMID 28376813, 2017). "However, and in an independent way, alterations in AXIN2 (loss-of-function, dosage dependent, or even gain-of-function mutations) can contribute to development of gastric cancer." (PMID 31632692, 2019). "Indeed, different components of the Wnt pathway have been shown to be mutated or dysregulated in gastric cancer, including Wnt1, SFRPs, Axin1 and Axin2, APC, GSK3-β, and β-catenin." (PMID 28230774, 2017). "Previous research has shown that frameshift mutations in Wnt pathway regulators like AXIN2 and TCF7L2 are common in gastric cancers with high MSI, further linking Wnt pathway dysregulation to tumor progression." (PMID 40444048, 2025). "Knockdown of FBXW2 (sh-FBXW2) promoted gastric cancer cell viability and invasion while increasing β-catenin expression and reducing GSK3β and Axin2 levels." (PMID 40225854, 2025). "We demonstrated that LPA-LPAR2 increased ATP production by both OXPHOS and glycolysis via the downregulation of Axin2, thereby providing energy sources for the proliferation, migration, and invasion of gastric cancer cells." (PMID 36551233, 2022). "We screened eight DDR-related genes (ZBTB7A, POLQ, CHEK1, NPDC1, RAMP1, AXIN2, SFRP2, and APOD) to establish a risk model, which can predict the prognosis of gastric cancer patients and guide the clinical implementation of immunotherapy." (PMID 36578802, 2022). "Although we demonstrated that CBX4 activates β-catenin signaling and its transcriptional activity, we did not identify or validate the specific downstream target genes (e.g., c-MYC, CCND1, AXIN2) responsible for mediating the oncogenic effects of CBX4 in gastric cancer." (PMID 41502529, 2025). "Despite extensive studies reporting the anti-tumor activity of AXIN2 in varying cancers, there are also studies indicating that it may also demonstrate oncogenic properties in colorectal, liver, and gastric cancers." (PMID 40746892, 2025). "We recently demonstrated that polymorphic variants in AXIN2 and CDH1, which are involved in cell adhesion and migration and are strongly related to breast and gastric cancer, are associated with NSOC, reinforcing the putative link between cancer and oral clefting." (PMID 32143304, 2020). "Though, the population size in our study is small and the significant results need to be confirmed in larger groups with known family history of breast and gastric cancer to better understand the interactions between AXIN2 and CDH1 genes in the development of NSCL ± P." (PMID 28376813, 2017). "Thus, targeting the specific LPAR2 receptor and Axin2 may provide a novel therapeutic approach for the treatment of gastric cancer." (PMID 36551233, 2022). "In gastric cancer, LPAR2 reduces AXIN2 expression, activating the Wnt/β-catenin pathway and promoting cancer cells to be proliferated, migrated and invaded." (PMID 40746892, 2025). "These potentially new gastric cancer driver genes, as well as genes with high nonclonal mutation frequency, such as STK11, GPS2, NDUFB9, and AXIN2, represent good candidates for inclusion in future studies of gastric tumorigenesis." (PMID 36970058, 2022). "Moreover, the analysis from database showed the positive correlation between expression of UBAP2L and that of wnt/β-catenin downstream target genes, CCND1, AXIN2, and MYC in gastric cancer tissues, suggesting that UBAP2L activated this signaling." (PMID 34823423, 2021). "Subsequently, 2,4-diamino-quinazoline (2,4-DAQ), a selective inhibitor of Lef1, was identified to suppress the expression of Wnt/β-catenin target genes such as AXIN2, MYC and LGR5 and result in the suppression of gastric cancer cell growth through the apoptotic pathway." (PMID 32824603, 2020).
gastric cancer (continued). "In human gastric cancer, EZH2 promotes the activation of Wnt/β-catenin signaling by down-regulating CXXC4 expression, and several other Wnt pathway antagonists, including NKD1, PRICKLE1, PPP2R2B, AXIN2 and SFRP5, were concordantly silenced by EZH2 in hepatocellular carcinomas." (PMID 27926488, 2017). "However, how LPA-LPAR2 and dysregulated Axin2 induce glycolysis and OXPHOS in the gastric cancer cell line was not clearly shown in this study, suggesting that a further investigation is required to reveal a more detailed molecular mechanism." (PMID 36551233, 2022).
hepatocellular carcinoma (16 papers, 2004 to 2026). A malignant tumor that arises from hepatocytes. "Next, we queried the TCGA liver carcinoma database to examine the expression of AXIN2 and LGR5 in HCC patient samples." (PMID 41550750, 2026). "Regarding the role played by gene mutations, changes in Hbx modulate the expression of Wnt-5a in hepatoma cells, whereas inactivating mutations in APC, AXIN1 and AXIN2 genes or methylation in APC aberrantly modify the Wnt signaling response." (PMID 37512809, 2023). "Molecularly, it was shown that EZH2 silences Wnt antagonists, such as DKK1 and AXIN2, leading to Wnt/β-catenin signaling activation in hepatocellular carcinoma." (PMID 37175580, 2023). "For instance, it has been found that miR-221-3p expression is remarkably up-modulated in hepatoma tissues and cells, and it facilitates cancer cell proliferation and migration through repressing Axin2." (PMID 34022918, 2021). "In addition, STRAP knockout in hepatocellular carcinoma decreased mRNA abundance of stemness markers and liver progenitor genes, including AXIN2, LGR5, CD133, and CD44." (PMID 34206917, 2021). "For example, in Nonalcoholic Fatty Liver Disease (NAFLD)-related Hepatocellular Carcinoma (HCC), HDAC8 and EZH2 regulated H4ac content and H3K27me3 levels of the AXIN2 gene, respectively." (PMID 39719443, 2024).